ACE (angiotensin I converting enzyme)
Diseases named in the same sentence as ACE in open-access papers (continued):
Sharing a sentence is not in itself a finding about the gene and the disease.
cancer (continued). "Consistently, the activation of ACE/Ang-II/AT1R axis promotes proliferation, invasion, angiogenesis, epithelial-mesenchymal transition (EMT), and resistance in several cancer models." (PMID 36335375, 2022). "In most cases, elevated expression of ACE and its downstream receptor AT1R is related with adverse characteristics and poor outcomes in cancer patients." (PMID 36335375, 2022). "ACE was only highly expressed in PCPG, CHOL, and KIRC tumor tissues, whereas it was expressed at low levels in 7 types of cancers." (PMID 34671200, 2021). "However, whether the anti-cancer effect of ACE is related to gut microbiota remains unclear yet." (PMID 34531745, 2021). "In this study, we comprehensively integrated and analyzed the molecular characteristics of 6 significant members of the RAS family across pan-cancer: AGT, ACE, ACE2, AGTR1, AGTR2, and MAS1." (PMID 34671200, 2021). "ACE was highly expressed in CHOL compared with normal tissue, supported a previous study reporting that ACE was highly expressed in cancer patients in serum level." (PMID 34671200, 2021). "In tumor tissue, AGTR2 and MAS1 were weakly expressed; in contrast, ACE and AGT presented broad expression across 33 cancer types." (PMID 34671200, 2021). "In THCA, the expression of ACE and AGTR1 was decreased in stage III/IV compared to stage I/II cancer." (PMID 34671200, 2021). "Genetic variations of RAS components (ACE and AT1R) affect their expression in breast tissue and, therefore, in cancer activity." (PMID 34539580, 2021). "CKD patients were more likely to be treated with iron preparations (CKD: 18.3%; cancer: 8.4%) or anti-hypertensive drugs (ACE inhibitor or ARBs) (CKD: 43.0%; cancer: 30.8%) than cancer patients." (PMID 31521117, 2019). "Renin angiotensin system (RAS) comprising Angiotensin II receptor type I (AGTR1), a receptor of Angiotensin II (Ang II) and Angiotensin converting enzyme (ACE), plays a critical role in many diseases including cancer." (PMID 29460395, 2018). "In this model, cancer event (p<0.001), age (p<0.001), ANP (p<0.001) and use of ACE-inhibitor (p = 0.003) or digitalis (p<0.001) were independently associated with AF." (PMID 30289944, 2018). "ACE, which was downregulated by NRP-1 in BT-474 cells has been reported to have pro-tumourigenic effects in various cancer types although its homologue ACE2 has anti-tumour roles." (PMID 29728077, 2018). "In addition, several experimental models recently suggested that angiotensin II could be involved in cancer development and progression and that RAS blockage by AT1-R antagonists or Angiotensin converting enzyme inhibitors (ACE-Is) could be useful in cancer therapy." (PMID 24967411, 2014). "In addition, considering the possible role of this polymorphism in serum ACE level, it is possible that the cancer risk may be modified by ACE level, but not by the variant." (PMID 22151803, 2011). "Tissue-specific regulation and embryonic origin may further contribute to the context-dependent roles of ACE and HSPB8 across cancers, warranting additional mechanistic investigation." (PMID 41490177, 2026). "Neither ACE nor HSPB8 has been systematically explored in carcinoma, underscoring the importance of further analyses and knockdown experiments in LUSC cells." (PMID 41490177, 2026). "Metformin, statins, aspirin, ACE inhibitors, and beta blockers have all demonstrated improved survival among individuals with cancer compared to those who do not receive these medications." (PMID 38491813, 2024). "As such, no long-term study has shown any beneficial effects of ACE inhibitors in childhood cancer survivors on improving quality of life, providing long-term benefits, or reducing progression to HF or death." (PMID 36670699, 2023).
cancer (continued). "Zn-dependent metalloproteases, such asmatrix metalloproteases (MMPs) and cell membrane-bound proteases, e.g., aminopeptidase N (APN), angiotensin converting enzyme (ACE) and neutral endopeptidase (NEP), are examples of enzymes involved in cancer development and reported to be inhibited by αAPs." (PMID 35743158, 2022). "There are also unambitious data from a recent review in cancer patients with longer follow-ups which tend to show that treatment with b-blockers and ACE inhibitors or ARBs does not prevent chemotherapy-induced cardiotoxicity." (PMID 36005423, 2022). "In the trial subsets where there was no ACE-inhibitor treatment in either of the study arms, there was again a statistically significant increase in cancers only if the cumulative exposure was >3 years." (PMID 35235571, 2022). "The liver may be a fertile ground for CRC metastasis due to its production of AGT, which CRC metastases could utilize via elevated levels of ACE to produce more ATII and drive cancer growth via AT1R-mediated mechanisms." (PMID 34428252, 2021). "Furthermore, ACE inhibitors and ATIIR1 antagonists, which inhibit ATII production and action respectively, appear to exert inhibitory effects on cancer progression, vascularization and metastasis." (PMID 30177970, 2018). "Surprisingly, there is not universal agreement on the effects of ACE inhibitors and ARBs on cancer incidence." (PMID 28791183, 2017). "Judging from the results of clinical studies, there is no reason to administer ACE inhibitors or ARBs for the prevention and/or treatment of cancer despite the favorable findings in experimental research." (PMID 27646033, 2016). "Indeed, ACE inhibitors suppressed VEGF expression, VEGF-induced angiogenesis and tumor growth and ARBs also showed similar effects in certain cancer cell lines and animal cancer models." (PMID 27646033, 2016). "Instructive in that clinical cancer growth inhibition via ACE inhibition occurs largely, although not exclusively, through angiogenesis inhibition, not inherent cytotoxicity." (PMID 25211298, 2014). "ACE inhibitors are known to block Ang II formation, and numerous studies have demonstrated that ACE inhibitors decrease cellular proliferation, VEGF expression, and inhibit angiogenesis in culture and in animal models of cancer." (PMID 20431722, 2010). "However, after a multidisciplinary discussion and the identification of noncaseating granulomas in the biopsy, along with elevated ACE levels, the focus shifted away from cancer recurrence or metastasis." (PMID 38459507, 2024). "Variables used were lowest hemoglobin during admission, lowest platelet count, lowest ANC, sex, BMI, medical history, ACE inhibitor use before admission, smoking status, age, and cancer status (having no cancer vs. having solid cancer vs. having hematologic cancer)." (PMID 39567199, 2024). "Indeed, there is no persuasive evidence that ACE inhibitors, ARBs, aldosterone antagonists, or b-blockers in survivors of adult cancers improve survival or quality of life when used for either primary or secondary prevention." (PMID 36005423, 2022). "In addition, ACE may regulate EMT, a central aspect of cancer progression and an essential part of metastasis." (PMID 33513805, 2021). "However, using this technique, Panyayai and coworkers reported WCW as the tripeptide with best inhibitory activity to angiotensin-I converting enzyme (ACE), an enzyme with tumor-promoting roles, and the inhibition of which shows reduced mortality and recurrence in many cancer types." (PMID 32069856, 2020). "It is essential that we continue to investigate ways of protecting the heart following cancer chemotherapy, At present the limited cardioprotective strategies available -- dexrazoxane, ACE-inhibitors, ARB, and beta-blockers -- are not in routine prophylactic use." (PMID 28185035, 2017).
cancer (continued). "Taken together, ACE and AGTR1 blockers could be used as an adjuvant therapy along with established chemotherapeutic drugs to further potentiate the anti-cancer effects of the conventional cancer therapies." (PMID 25981295, 2015). "Although previous studies revealed possible roles of ACE in cancer etiology, our result suggested that these roles may not account by the variant of ACE gene." (PMID 22151803, 2011). "ACE inhibitors may be of some benefit in cancer, mainly acting via their antiangiogenic potential and as more general zinc metalloprotease inhibitors, independently of the RAS and of ACE inhibition." (PMID 14997208, 2004). "Therefore, the pattern of ACE expression in cancer cell lines may not correlate perfectly well with that in bulk tumor tissues." (PMID 33858332, 2021). "Some evidence suggests that these drugs may prevent fibrosis and cancer in existing NAFLD; however, more studies are needed, and no studies have examined if ACE inhibitors can prevent the development of NAFLD." (PMID 36504827, 2022).
tumor (210 papers, 2004 to 2026). "The expressions of AT1R in tumor cells and ACE in tumor vessels are associated with aggressive behavior in ccRCC." (PMID 40149923, 2025). "After further adjustment for comorbidities, tumor extent and primary treatment the risk association persisted for diuretics (HR 1.10, 95% CI 1.01–1.19) and ACE-inhibitors (HR 1.10, 95% CI 1.01–1.21)." (PMID 34921656, 2022). "A significant reduction on VEGF-A mRNA and protein, in association with attenuated tumor growth, was also observed in Lewis lung tumors following candesartan administration, an ACE inhibitor." (PMID 32503281, 2020). "It reported that ACE inhibitor perindopril-inhibited tumor growth was associated with the suppression of angiogenesis." (PMID 32581212, 2020). "Angiotensin II can stimulate tumor neovascularization, and over expressions of ACE and angiotensin II type 1 receptor have been associated with tumor growth, metastasis, and progression." (PMID 31312309, 2019). "As the role of RAS system has been characterized in tumor development, the aim of the present study was to investigate the association between the ACE I/D, and A1166C polymorphisms and UL." (PMID 31554351, 2019). "It has been shown that angiotensin I-converting enzyme inhibitors (ACEIs) and angiotensin II type-1 receptor blockers (ARBs) can decrease tumor growth and tumor-associated angiogenesis and inhibit metastasis." (PMID 26883083, 2016). "ACE inhibition is associated with a reduction in tumor growth for several malignancies including breast, prostate, lung, and colon cancer." (PMID 20380732, 2010). "AGT is released in the tumour pseudocyst in vivo in humans, and ACE is expressed by tumour-associated vasculature, suggesting a potential production of all RAS components in the tumour environment." (PMID 14997208, 2004). "We hypothesized that the increased sensitivity to IR due to ACE overexpression is associated with increased levels of intracellular ROS in tumor cells." (PMID 37371679, 2023). "Similarly, one systematic review investigated the association between ACE inhibitors and ARBs, which have the potential to promote tumor growth, and found a 6% decreased risk in all-site CRC in pooled analysis." (PMID 34224060, 2021). "Thus, imbalances in components of the intrarenal RAS, such as the up-regulation of AT1Rs in RCC cells and ACE in tumour vessels, have been associated with renal cancer development and progression." (PMID 33578778, 2021). "Otherwise, it has been reported that angiotensin I-converting enzyme inhibitors (ACEI) could decrease tumor growth and tumor-associated angiogenesis and inhibit metastasis." (PMID 28533754, 2017). "Epidemiologic studies have indicated that inhibition of ACE activity could suppress tumor growth and angiogenesis, decreasing the risk and mortality rate." (PMID 25889770, 2015). "THP-1 cells expressing increased ACE (termed THP-1-ACE) constitute a human macrophage model with increased PPARα that shows enhanced cytotoxicity against tumor cells and better phagocytosis and killing of MRSA." (PMID 39910334, 2025). "Renin-angiotensin system inhibitors, including ACE inhibitors and angiotensin receptor blockers (ARBs), have demonstrated anti-tumor effects in preclinical models." (PMID 40940839, 2025). "The effect of this drug in vivo was striking: tumor reduction in both WT and A10-PPARα mice had a somewhat synergistic effect with the increased ACE present in A10-PPARα mice." (PMID 39910334, 2025). "Renin–angiotensin system (RAS) inhibitors, such as ACE inhibitors and ARBs, have been suggested to improve prognosis by modulating tumor microcirculation and suppressing proliferative signaling." (PMID 41303903, 2025). "In Case 1, ACE was elevated while all other routine blood tests were within normal ranges; tumor markers were also normal, helping to exclude malignancy." (PMID 41200618, 2025).
tumor (continued). "The imbalance of the renin–angiotensin system (RAS), characterized by the overactivation of the pro-tumor ACE/AngII/AT1R axis, is closely linked to tumor growth, angiogenesis, metastasis, and poor prognosis." (PMID 41301459, 2025). "In Case 2, inflammatory markers were mildly elevated, while the ACE level was within normal limits, and tumor markers were again unremarkable." (PMID 41200618, 2025). "β-blockers, such as propranolol, demonstrate significant tumor-inhibitory effects, and ACE-Is/ARBs have shown tumor regression in xenograft models." (PMID 41303679, 2025). "In CC-RCC, the overexpression of ACE correlates with unfavorable outcomes and influences tumor invasion and metastasis." (PMID 41301459, 2025). "ACE10/10 mice, possessing increased ACE expression in macrophages, exhibit enhanced anti-tumor immunity and anti-bactericidal effects compared to those of wild type (WT) mice, while the detailed molecular mechanism has not been elucidated yet." (PMID 38746124, 2024). "Preclinical studies revealed an upregulation of AT1R in tumor cells, as well as an increased expression of ACE in tumor vessels, in CCRCCs with a poorer prognosis." (PMID 38338778, 2024). "Other drugs, such as ACE inhibitors, have been used to improve tumor perfusion and enlarge endothelial gaps and enhance nanomedicine delivery to tumors." (PMID 38790986, 2024). "PPARα depletion impaired cytokine production and antigen-presenting activity in ACE-overexpressing macrophages, resulting in reduced tumor antigen-specific CD8+ T cell activity." (PMID 38746124, 2024). "The effects of ACE/NEP inhibition were investigated as well to reveal the best candidates for subsequent evaluation in tumor-bearing mice." (PMID 37631306, 2023). "A study with the ACE inhibitor losartan supports these findings by stimulating a proapoptotic pathway reducing tumor growth and enhancing tumor cell necrosis." (PMID 36768635, 2023). "Proteolytic probiotics are commonly used to produce peptides from milk that exhibits anti‐tumor, immune‐stimulatory, opioid, antihypertensive, and ACE inhibitory bioactivity." (PMID 37701240, 2023). "Serum ACE levels and mediastinal lymph node size were significantly reduced at subsequent tumor occurrence." (PMID 35744031, 2022). "Our results showed that ACE-27 status was an independent prognostic factor for clinical outcomes after adjusting for tumor characteristics." (PMID 35326617, 2022). "It has been widely described that the AngII/ACE/AT1 pathway induces tumor progression and metastasis in various tissues." (PMID 35409002, 2022). "One, yet unexplored route, concerns the angiotensin-converting enzyme (ACE)–angiotensin pathway, where the overexpression of ACE in monocytic cells was shown to reduce the generation of MDSCs, while angiotensin was able to reduce the tumor malignancy in PC." (PMID 35860573, 2022). "Multivariate analysis showed that increasing ACE-27 score, higher primary tumor stage, and higher tumor grade were all significant prognostic factors for PFS and CSS." (PMID 35326617, 2022). "For example, ACE inhibition leads to the accumulation of bradykinin, an inflammatory mediator involved in tumor growth and metastasis." (PMID 35113855, 2022). "ACE expression was observed in the cytoplasm and cell membrane of tumor cells and furin staining was limited to the cytoplasm in a granular pattern." (PMID 35681562, 2022). "Especially ARBs and ACE-inhibitors are highlighted as most beneficial groups, but knowledge of their independent impact on tumor progress is limited since mostly they are combined with some other antihypertensive medication drug group." (PMID 34921656, 2022). "Angiogenesis-dependent tumor growth and potential metastatic characteristic was found to be reduced when applying ACE-inhibitors in murine model." (PMID 34921656, 2022). "Reduction of angiotensin-converting enzyme (ACE) activity in tumor tissue correlating with poor prognosis and tumor metastasis is yet another problem." (PMID 36211566, 2022).